Y_RNA (Y RNA )
Gene: Miscellaneous RNA gene on chromosome 5 (132,468,147 to 132,468,257, forward strand). Ensembl gene ENSG00000202533.
Homologues: Orthologues: chimpanzee Y_RNA (100% identical), macaque Y_RNA (95% identical). Paralogues in human: RNY1 (95% identical), Y_RNA (90% identical), Y_RNA (89% identical), Y_RNA (88% identical), Y_RNA (87% identical), Y_RNA (86% identical), RNY1P11 (86% identical), Y_RNA (85% identical), RNY1P7 (84% identical), RNY1P8 (84% identical), Y_RNA (84% identical), RNY1P12 (83% identical), and 99 more.